C3 (complement C3)
Diseases named in the same sentence as C3 in open-access papers (continued):
Sharing a sentence is not in itself a finding about the gene and the disease.
COVID-19 (continued). "Activation of the complement system might be involved in the worsening of renal symptoms since deposition of C3 was significant in renal arteries and in glomerular capillaries of COVID-19 biopsies." (PMID 35350780, 2022). "Indeed, targeting both C3 and C5 within the complement cascade as a way to treat COVID-19 shows promise." (PMID 35860286, 2022). "Early clinical reports indicates that C3 inhibition therapy holds potential anti-inflammatory properties in COVID-19 and anti-complement C5 therapy in patients with severe COVID-19 lead to a drop in inflammatory markers and a successful recovery." (PMID 34335279, 2021). "Elevated levels of complement C3 (odds ratio [OR] 15.6, 95% CI 2.41–122.3; p = 0.039) are particularly associated with the risk of developing severe COVID-19 specifically in young patients, whereas no such influence seems to exist for elderly patients." (PMID 33846344, 2021). "As the list of COVID-19-associated pathophysiology linked to deregulated complement activation grows longer, it has become clear that complement inhibitors against C3 or C5 or activating pathways open new windows of therapeutic opportunity for treatment with severe COVID-19 cases." (PMID 33811541, 2021). "We conducted a systematic review and meta-analysis with meta-regression to investigate possible differences in the serum concentrations of two routinely measured complement components, C3 and C4, in COVID-19 patients with different severity and survival status." (PMID 34163491, 2021). "In an independent (bulk) RNA-seq dataset of bronchoalveolar fluid cells from (n=8) patients with COVID-19 and (n=20) uninfected controls, we found similar enrichment of complement genes in cells from patients, including significantly higher expression of C3 and CFB." (PMID 33827897, 2021). "For CVD + CKD + COVID-19, the targets were C3, TLR4, MAPK14, and CYBB." (PMID 34067609, 2021). "Median values of C3 and C4 levels in critical COVID-19 patients (group 3) were 116 mg/dL (108.0–127.7) and 26.0 mg/dL (17.0–39.0), respectively, whereas in mild and severe patients (groups 1 and 2), the median values were 125 mg/dL (105.5–145.5) and 26.5 mg/dL (21.0–33.0), respectively (p > 0.05)." (PMID 34422145, 2021). "Our second pathway-based identified target, C3, is upregulated in various CKDs and COVID-19." (PMID 34067609, 2021). "Besides, the upstream location of C3 signals in the innate immunity is also asserted for the superior anti-inflammatory effect of the C3-blocking in COVID-19 patients with AMY-101 (a potent C3 inhibitor drug)." (PMID 34447458, 2021). "Eligibility criteria were a) reporting continuous data on serum C3 and C4 concentrations in COVID-19 patients, -b) investigating COVID-19 patients with different disease severity and/or survival status, c) adult patients, d) English language, e) ≥10 patients, and f) full-text available." (PMID 34163491, 2021). "Also, several anti-complement drugs are under development for use in COVID-19, such as C3 inhibitors of the compstatin family, which recently was shown to induce recovery and a drop in several major inflammatory parameters." (PMID 33692801, 2021). "A recent study shows that anti-C3 inhibitor AMY-101 successfully treats COVID-19 patients." (PMID 33200027, 2020). "Both C3 cleavage products C3c and C3d were strongly detected in renal arteries but also occurs in glomerular capillaries of COVID-19 biopsies, while tubular C3d was stronger than C3c in biopsies from COVID-19 patients." (PMID 33584662, 2020). "When compared the COVID-19 group with the CAP and normal control groups, respectively, the mean value of CRP and SAA in the COVID-19 group (including mild, moderate and severe patients) had increased significantly (P < 0.01), whereas the mean values of C3, C4 and PA decreased (P < 0.01)." (PMID 32713370, 2020).
COVID-19 (continued). "Immunohistochemistry analysis of lung tissue from patients who died of COVID-19 revealed deposition of complement components mannose-binding lectin, C4, C3 and the terminal membrane attack complex C5b-9 in alveolar epithelial/inflammatory cells and alveolar spaces." (PMID 34192268, 2020). "Similarly, allele A lost its significance as a risk factor for susceptibility and mortality in COVID-19 when polymorphisms of angiotensin-converting enzyme 1 (ACE1) and complement component 3 (C3) were added to the multivariate regression model." (PMID 33330542, 2020). "Level of C3 protein was suggested as a predictor of mortality of COVID-19 patients." (PMID 32916812, 2020). "In addition, the functions of B cells and complements were tested, including IgM, IgG, IgA, IgE, C3, and C4, for both mild and severe COVID-19 cases." (PMID 32983157, 2020). "Furthermore, TF activation has been reported in the presence of SARS-CoV-2, and there is evidence that TF expression can be disrupted by inhibiting the complement component C3, suggesting that the complement axis plays a critical role in COVID-19-induced inflammation." (PMID 38933264, 2024). "Therefore, we compared the admission (pretreatment) plasma levels of C1q, C2, C4, C4b, MBL, C5, C5a, C3, C3b, factor B, factor D, factor H, and factor I between children with COVID-19 who developed moderate or severe disease and those who developed only mild disease." (PMID 36961465, 2023). "Notably, the C3 inhibitor AMY-101 has been used in four patients with COVID-19, who recovered; the C5 activation inhibitor, eculizumab, as adjunctive treatment in 14 patients, 12 of whom recovered; another anti-C5a antibody (BDB-001) was used in 2 patients with critical COVID-19, who recovered." (PMID 33827897, 2021). "To determine whether the lectin pathway contributes to COVID-19 pathogenesis, we measured the plasma concentration of 11 lectin complement proteins and C3dg, a marker of C3 activation, in a population of patients with severe kidney impairment, the majority of whom were of non-European ancestry." (PMID 33995410, 2021). "However, young patients have more active immune function, which is why elevated levels of serum complement C3 may be a potential indicator of the severity of COVID-19 patients." (PMID 33846344, 2021). "Also, increased plasma levels of sC5b-9 complexes have been found in COVID-19 patients, deposition of C4d and C3 has been detected in the lungs of diseased patients and binding of MBL and MBL associated serine protease (MASP)-2 of the LPW to virus proteins of the SARS CoV-2 virus has been reported." (PMID 33692801, 2021). "Therefore, C3 inhibition may be a prospective therapeutic approach to inhibit complement activation, and complement-mediated inflammatory and immune response in COVID-19 patients." (PMID 33664741, 2021). "Interestingly, the C3 inhibitor AMY-101 has already shown efficacy in COVID-19." (PMID 32485958, 2020). "In our study, we found there were higher levels of C3 and C4 in SARS-CoV-2 sepsis patients, thus we believe that the treatment of inhibiting hyperactivation of the complement system in SARS-CoV-2 sepsis may be worthy of further study." (PMID 33329592, 2020). "As COVID-19 progresses, platelets internalize circulating viral particles and activate TLR7, triggering complement component C3 release, which also promotes neutrophil extracellular trap formation (NETosis)." (PMID 40282925, 2025). "HEP6 and HEP7 cells had similar profiles to those in the HEP2 subset but with high expression of acute phase proteins in HEP7 (e.g., CRP, C3, C4a, SAA1, and FTH1; a COVID-19 specific cluster; below) or apoptosis and cellular senescence pathways in HEP6." (PMID 40087773, 2025). "Pronounced expression of complement proteins (C1q, C3, C3b, C4, C5) and inflammatory cytokines (TNF, IL-1α, and IL-17A/E) was detected in the fetal compartment of COVID-19-affected pregnancies." (PMID 39390219, 2024).
COVID-19 (continued). "Lastly, C3, CXCL11, and CCL5 are established immune proteins that were elevated in our MIS-C cohort and have been previously identified to be elevated in COVID-19 patients." (PMID 38632526, 2024). "This study aimed to evaluate the levels of immunological biomarkers such as CRP, C3, C4, IL-8, IL-10, IL-12, TNF-α, and IFN-γ in patients with COVID-19 and bacterial pneumonia." (PMID 38585537, 2023). "COVID-19 patient levels for CH50, sC5b-9, C5a, C5, C3a, C3, and factor B were all higher than levels in healthy individuals." (PMID 37731491, 2023). "In addition, children with MIS-C had significantly elevated levels of C3 (318.2 [70.7] ng/mL vs 237.7 [61.8] ng/mL), C5a (2614 [336.2] ng/mL vs 1826 [541.0] ng/mL), and mannose-binding lectin (79.4 [12.4] ng/mL vs 69.6 [14.7] ng/mL) in comparison to children with acute COVID-19." (PMID 36961465, 2023). "Among them, C3 population (high activity of OCT1 and CREB) decreases and C4 population (high activity of CEBP and TEF) increases during COVID-19 progression from healthy to moderate to severe." (PMID 36641532, 2023). "Immunohistochemical analysis of COVID-19 lung autopsies reveals high expression of the complement components MBL, C4, C3, and C5b-9 in alveolar epithelial cells, as well as in COVID-induced acute kidney failure." (PMID 35401519, 2022). "Therefore, the dysregulation in C3 and HBB serum protein levels observed in COVID-19 cohorts and previously reported in response to α-Gal51 may be due to gut microbiota dysbiosis associated to SARS-CoV-2 infection and COVID-19 severity." (PMID 34566994, 2021). "Therefore, C3 inhibitors may work in COVID-19 patients with pre-existing CKDs." (PMID 34067609, 2021). "A single case report using the investigational C3 inhibitor, AMY-101, in a patient with severe COVID-19 related ARDS showed complete recovery." (PMID 32932930, 2020). "Compared with the results of CAP and normal control groups, the mean values of C3, C4, CRP, SAA and PA in the COVID-19 group (including mild, moderate and severe patients) showed significant changes (P < 0.01)." (PMID 32713370, 2020). "Meanwhile, the statistical analyses indicated that the development of COVID-19 brought about a significant increase in the content of CRP and SAA (P < 0.01), and a decline in the content of C3, C4 and PA (P < 0.01)." (PMID 32713370, 2020). "Our patient, who had a known pathogenic C3 GOF variant, developed aHUS following COVID-19, despite having had other viral infections without subsequent aHUS earlier in his life." (PMID 39917338, 2025). "In additional experiments, we also investigated the potential action of the nutraceutical formula on other inflammatory genes with a role in innate immunity (i.e., C3, IL-1β, IL-6, CXCL10 and CXCL12) whose modulation have been reported in COVID-19 pathogenesis and progression." (PMID 38886736, 2024). "While these maladaptive effects are particularly severe in COVID-19 and RSV, the role of the complement system in influenza A is complicated (namely, C3 may be protective while C3a-C3aR, C5a-C5aR may be harmful to the host)." (PMID 38368584, 2024). "C3, C4 and C5 knockout mice together with Crry, DAF, C3aR and/or C5aR1 and C5aR2 knockout can be used for defining the role of complement in general and C3a-C3aR and C5a-C5aR signaling in the pathogenesis of severe COVID-19 and long COVID-19." (PMID 38368584, 2024). "In order to explore potential activation of the C system in breast milk due to immunization against COVID-19, we subsequently examined the amounts of C1q, MBL, and C3, the first recognition subcomponents of the classical, lectin, and alternative pathways, respectively." (PMID 36901824, 2023). "Our results do not, however, provide evidence that increased levels of C3, C5, and C5a characterize by COVID-19 in contrast to other pulmonary infections." (PMID 37239041, 2023).
COVID-19 (continued). "Individual NET-specific/related biomarkers were featured in single expression graphs, where plasma phospholipase (PLC1 and PLCγ), CAS1, and PDA4 were significantly upregulated in Long-COVID, while NFkB, CR1, C3 and SLPG were depressed, compared to severe COVID-19." (PMID 37301958, 2023). "The ~ 115 kDa complement C3 band was predominantly present in healthy plasma samples and acute COVID-19 plasma samples but not in convalescent COVID-19 plasma samples." (PMID 36765106, 2023). "There was a strong association between C3 and CRP in patients with bacterial pneumonia (R=0.591; P<0.001) and a weak negative correlation with COVID-19." (PMID 38585537, 2023). "Immuno-histochemical analysis of lung tissue in death of patients with COVID-19 showed that complement components mannan-binding lectin (MBL), C3, C4 and C5b-9 in exudates of alveolar spaces, some pneumocytes, alveolar epithelial cells and inflammatory cells were strongly stained." (PMID 34321065, 2021). "Blood tests to measure neutrophil/lymphocyte ratio (NLR) and levels of ferritin, CRP, D-dimer, complement components (C3 and C4), cytokines, and lymphocyte subsets, as well as SARS-Cov-2 RT-PCR tests, were performed in COVID-19-confirmed cases within 48 hours of admission." (PMID 34422145, 2021). "A recent preprint study reported that the paraformaldehyde-fixed lung tissue from patients who died of COVID-19 revealed strong expression of complement components MBL, MASP-2, C4a, C3, and the terminal MAC C5b-9, suggesting LP complement hyper-activation occurred in the lungs of COVID-19 patients." (PMID 33811541, 2021). "Since IFN-α and C3 are identified as common targets in CKD and COVID-19, these two targets may be specifically explored to treat COVID-19 patients with pre-existing CKDs." (PMID 34067609, 2021). "In brief, despite nonconclusive studies, the available data suggested favorable outcomes in a small number of patients with severe COVID-19 treated either with C1 inhibitor, MASP-2 monoclonal antibodies, compstatin-based complement C3 inhibitor, anti-C5 drugs, or C5a-C5aR1 antagonists." (PMID 34567008, 2021). "In this context, a retrospective study constituting 57 hospitalized patients with COVID-19 reported nonsignificant differences in C3 and C4 serum levels among the critically and moderately ill patients with SARS-CoV-2 infection." (PMID 34066983, 2021). "Neither our study nor a previously published report found lower C3 or C4 levels in severe COVID-19 patients, although a relationship between PE and low C4 levels cannot be excluded." (PMID 34422145, 2021). "The underlying mechanisms of the pathogenesis and infection of S-COVID-19 could be better described by suggesting APP, EGF, C3, APOE, and APOA1 as the novel chief organizers of the network foundation." (PMID 33244380, 2020). "Notably, some proteins, such as C3 or CST3 are increasing in the presented cohort but not across all COVID-19 studies." (PMID 41430040, 2025). "Similarly, in previous reports, FGB, FGG, complements C4, C3, C5, C2, C9, and complement C1q subcomponent subunits A, B, and C (C1QA, C1QB and C1QC) were found to be upregulated in the lung tissues of patient with COVID-19." (PMID 38882332, 2024). "We found no significant increase in the proportion of C3+ astrocytes in COVID-19 vs. ARDS." (PMID 37483351, 2023). "The inhibition of C3, which is upstream of C5 in the complement cascade, does not appear to be a safe approach for patients with COVID-19, since it could reduce the antiviral response and prevent immunity to other infectious diseases." (PMID 36304162, 2022). "Several explanations have been proposed for the advantage of being a non-menopausal female against COVID-19, notably lower levels of pro-inflammatory molecules, such as complement component 3 (C3), interleukin-2R, interleukin-6, interleukin-8, and TNF-α in non-menopausal women." (PMID 35872674, 2022).
COVID-19 (continued). "Interestingly, when comparing AH in the RO group transplanted with GTKO porcine cornea with that in the survival group, six proteins (C3, C5, C7, C9, C8B, and C8G) were enriched in the “Coronavirus disease - COVID-19” KEGG pathway (data not shown)." (PMID 35401527, 2022). "However, another study stated the levels of C3 and C4 were increased in 57.2% and 36.9% of COVID-19 patients comparing to the negative controls." (PMID 36094909, 2022). "Zinellu & Mangoni found that C3 and C4 concentrations were significantly decreased, indicating increased complement activation, in patients with more severe COVID-19 in the non-pregnant population and that increased complement activation was significantly associated with greater mortality." (PMID 36383608, 2022). "Using a random-effects model, standardized mean differences (SMD) with 95% confidence intervals (CIs) were calculated to evaluate differences in serum C3 and C4 concentrations between COVID-19 patients with low vs. high severity or survivor vs. non-survivor status." (PMID 34163491, 2021). "We noticed that complement C3 and C4 were reduced in the non-survivors, indicating that the dysregulated complement system may be activated in COVID-19." (PMID 33664741, 2021). "The top five targets identified based on candidate gene prioritization were C3, CFB, EGFR, IL6, and TLR2, where the 39 common core genes were used as a test set, and 1899 genes from the COVID-19 pathway (KEGG) and our multi-omics datasets were used as training sets." (PMID 34067609, 2021). "Clinical studies, including the use of C3 blocking peptides such as AMY-101, are in the progress of illustrating a potential regulation in the aggravated inflammatory reaction, lung damage, and multiple organ failure, which have been found in some COVID-19 instances." (PMID 34066983, 2021). "Compared to the dialysis control cohort, samples from patients with non-severe COVID-19 had higher levels of the lectin PRMs M-ficolin (p=0.02) and CL-K1 (p=0.007) and the C3 activation marker C3dg (p=0.02), but lower CL-L1 (p=0.02), MASP-3 (p=0.008) and MAp19 (p=0.008) levels." (PMID 33995410, 2021). "Likewise, lung samples collected at autopsy from patients with COVID-19 showed a positive linear relationship between SARS-CoV-2 viral loads and C3 mRNA expression, consistent with the dose-dependency observed between these two parameters on experimental SARS-CoV-2 infection." (PMID 33827897, 2021). "Interestingly, the COVID-19 non-survivors presented lower levels of C3 and C4 proteins at admission in comparison to patients who recovered." (PMID 32916812, 2020). "Therefore, plasma levels of C3 alone may not be a reliable marker for predicting COVID-19 progression." (PMID 36765106, 2023). "Furthermore, other proteins mediators of complement, such as C3, C4, and C5b-9, as well as inflammatory cells were found to be significantly increased in alveolar epithelial cells of the non-survivors infected with COVID-19." (PMID 34276659, 2021). "Proximal complement inhibitors that primarily target the C3 complement system may be potential candidates for COVID-19, although these are still in clinical research and none of them have been approved and only minimal evidence is available from Phase II clinical trials." (PMID 34447458, 2021). "The use of the C3 inhibitor AMY-101 in one patient withCOVID-19, who recovered, and the C5 activationinhibitor, eculizumab, as adjunctive treatment in four patients, who recovered, provide clinical evidence that complement may play apathogenic role in COVID-19." (PMID 32702726, 2020). "There were no signal inflows unique to either moderate or severe COVID-19 alone, whereas inflow through TNFRSF12A (due to TNFSF12) and ITGAX and ITGB2 (due to C3) drive outflows in only healthy controls." (PMID 39187683, 2024).